IFNA4 (interferon alpha 4)
Description:
Produced by macrophages, IFN-alpha have antiviral activities. Interferon stimulates the production of two enzymes: a protein kinase and an oligoadenylate synthetase.
Synonyms: MGC142200; IFN-alpha4a; INFA4
Tractability: Antibody: a drug acting on it is in phase 2 or 3 trials; its Gene Ontology location is reachable by antibodies, with high confidence; UniProt places it where antibodies can reach, with medium confidence; UniProt predicts a signal peptide or a membrane-spanning region.
Gene: Protein-coding gene on chromosome 9 (21,186,618 to 21,187,587, reverse strand). Ensembl gene ENSG00000236637.
Subcellular location: Secreted
Pathways (Reactome):
Immune System: Interferon alpha/beta signaling; Regulation of IFNA/IFNB signaling; TRAF6 mediated IRF7 activation
Disease: Evasion by RSV of host interferon responses; SARS-CoV-2 activates/modulates innate and adaptive immune responses
Hemostasis: Factors involved in megakaryocyte development and platelet production
Gene Ontology:
Molecular function: protein binding; cytokine activity; type I interferon receptor binding; cytokine receptor binding
Biological process: adaptive immune response; B cell activation involved in immune response; cellular response to virus; humoral immune response; natural killer cell activation involved in immune response; response to exogenous dsRNA; response to virus; T cell activation involved in immune response; type I interferon-mediated signaling pathway; defense response
Cellular component: extracellular region
Genetic constraint (gnomAD): Loss-of-function variants: 0 observed, 0.29 expected, observed/expected ratio (o/e) 0, 90% interval 0 to 1.87. That is too few expected variants to judge how well the gene tolerates losing a copy. Missense variants: 225 observed, 207.37 expected, observed/expected ratio (o/e) 1.09, 90% interval 0.97 to 1.21. Synonymous variants: 84 observed, 80.58 expected, observed/expected ratio (o/e) 1.04, 90% interval 0.87 to 1.25.
Homologues: Orthologues: macaque IFNA10 (93% identical), macaque IFNA21 (92% identical), pig IFN-ALPHA-9 (69% identical), pig IFN-ALPHA-13 (69% identical), pig IFN-ALPHA-15 (69% identical), pig IFN-ALPHA-8 (68% identical), pig IFNA1 (68% identical), pig IFN-ALPHA-4 (66% identical), pig IFN-ALPHA-17 (65% identical), pig IFN-ALPHA-1 (64% identical), pig IFN-ALPHA-10 (64% identical), rabbit IF1AD2 (63% identical), and 32 more. Paralogues in human: IFNA10 (96% identical), IFNA17 (96% identical), IFNA7 (94% identical), IFNA21 (92% identical), IFNA16 (89% identical), IFNA14 (84% identical), IFNA5 (84% identical), IFNA2 (81% identical), IFNA6 (81% identical), IFNA8 (81% identical), IFNA13 (80% identical), IFNA1 (80% identical), and 4 more.
Diseases named in the same sentence as IFNA4 in open-access papers:
IFNA4 is named in the same sentence as 31 diseases in open-access papers, as found by Europe PMC text mining. Sharing a sentence is not in itself a finding about the gene and the disease. The quoted sentences say what the papers report.
viral infection (12 papers, 2009 to 2022). "Phosphorylation of the constitutively expressed transcription factor IRF3 early in the cellular response to viral infection is a key event in the initial transcriptional activation of the mouse Ifna4 and Ifnb1 genes." (PMID 31076606, 2019). "Anti-HMGB1 also significantly reduced the viral infection in the lungs of RAGE deficient mice, and significantly increased IFNα4 and IFNγ expression in the lung compared to mice treated with the isotype control." (PMID 28099113, 2017). "The mRNAs encoding IFNβ-dependent genes, such as IRF7, IFNα4, and IFNα6, as well as CXCL10 an established marker of viral infection, were also suppressed in DEAF1−/− MEFs." (PMID 23846693, 2013). "In that context, virus infection readily induces the transcription of the Ifnb1 and Ifna4 genes." (PMID 34015056, 2021). "IFNβ, IFNα4, and IFNα2 transcripts could be detected as early as 4 h after virus infection." (PMID 22291574, 2012).
COVID-19 (5 papers, 2021 to 2023). A disease caused by infection with severe acute respiratory syndrome coronavirus 2. "This exercise revealed that, whereas the DS IFN score tracks preferentially with IFNG and IFNL1 in DS, this same ISG signature correlates significantly with eight different IFNs in COVID-19, five of which are type I IFNs (i.e., IFNA2, IFNA7/17/21, IFNA1, IFNA4/16, and IFNA10)." (PMID 37379383, 2023).
melanoma (3 papers, 2012 to 2025). A malignant, usually aggressive tumor composed of atypical, neoplastic melanocytes. "This was systematically evaluated by transplantation of B16 murine melanoma cells secreting five unique IFNα subtypes (B16_IFNα2; B16_IFNα4; B16_IFNα5; B16_IFNα6; B16_IFNα9) into a pre-clinical murine model." (PMID 32308653, 2020). "In addition, the secreted IFNα4, IFNα5, and IFNα9 could upregulate H-2Kb on both B16_IFNα and WT B16 melanoma cell lines." (PMID 32308653, 2020). "Furthermore, we demonstrate in another model that local delivery of IFNα9, but not IFNα4, significantly enhances tumor control by bolstering the capacity of transferred tumor-specific T cells to target melanoma." (PMID 32308653, 2020). "Nor would expression of IFNA4, which has been used in melanoma therapy." (PMID 22745913, 2012).
gastric cancer (2 papers, 2022 to 2024). A primary or metastatic malignant neoplasm involving the stomach. "A recent investigation has revealed that the expression of five genes linked to the cGAS-STING pathway, namely IFNB1, IFNA4, IL6, NFKB2, and TRIM25, exhibits potential as a valuable prognostic marker for OS in patients suffering from gastric cancer." (PMID 38240703, 2024).
herpesvirus infections (2 papers, 2023 to 2024). "There is a high prevalence of anti-cytokine antibodies, especially anti-IFNα, in patients with APS-1, and the higher level of autoantibodies against IFNα4 associates with more severe herpesvirus infections in APS-1 patients." (PMID 38829425, 2024).
breast tumors (1 paper, 2023). "A possible relationship between type I IFNs and CD169-expression on Mo-M was supported by mRNA data from primary human breast tumors, where mRNA expression for the gene SIGLEC1 encoding CD169 significantly correlated with IFNA4 (P=6.25e-04) and IFNB1 (P=5.53e-41)." (PMID 37404831, 2023).
colitis (1 paper, 2015). Inflammation of the colon. "To further evaluate the function of IFNA4 and IFNA10 during inflammation, we administrated recombinant IFNA4 and IFNA10 in a DSS-induced acute colitis model." (PMID 26000985, 2015).
HCMV infection (1 paper, 2025). "In the context of UL88-STOP-mCh HCMV infection, we also observed upregulation of the Type I interferons IFN-β and IFN-α2, although IFNα1, IFNα4, and IRF3 were similarly expressed after infection with TB40/E-mCh or UL88-STOP-mCh HCMV." (PMID 40638072, 2025).
hypothyroidism (1 paper, 2022). Abnormally low levels of thyroid hormone. "On the other hand, upregulation of IFNA4 was only observed in neuropathy and hypothyroidism and expression of OR4k15 was increased significantly in neuropathy and PCOS as shown by Boxplots 8I and 8K, respectively (P < 0.01)." (PMID 36175575, 2022).
influenza (1 paper, 2011). An acute viral infection of the respiratory tract, occurring in isolated cases, in epidemics, or in pandemics; it is caused by serologically different strains of viruses (influenzaviruses) designated A, B, and C, has a 3-day incubation period, and usually lasts for 3 to 10 days. "The protective effect of a vaccinia virus-vectored vaccine against influenza, on the other hand, was not improved by IFNβ or IFNα4 co-administration." (PMID 21943056, 2011).
intrauterine growth restricted (1 paper, 2023). "It has been confirmed that IFNA4 is significantly overexpressed in male intrauterine growth restricted (IUGR) rats and has a close association with multiple inflammatory pathways." (PMID 37700485, 2023).
Obesity (1 paper, 2023). Accumulation of substantial excess body fat. "For example, the prevalence of Brd4 promotes obesity associated inflammation and overexpression of proinflammatory cytokines, such as interferons (IFNA4), are associated with obesity pathogenesis, which are both elevated only in the FED group." (PMID 38720938, 2023).
osteoporosis (1 paper, 2023). A condition of reduced bone mass, with decreased cortical thickness and a decrease in the number and size of the trabeculae of cancellous bone (but normal chemical composition), resulting in increased fracture incidence. "Then five key genes (CCR5, IAPP, IFNA4, IGHV3-73 and PTGER1) were identified and used as features to construct a predictive prognostic model for osteoporosis using the GSE7158 dataset." (PMID 37361541, 2023). "Immunity plays an important role in the development of osteoporosis.CCR5, IAPP, IFNA4, IGHV3-73 and PTGER1were play an important role in the occurrences and diagnosis of OP." (PMID 37361541, 2023).
Salmonella Infections (1 paper, 2016). Infections with bacteria of the genus SALMONELLA. "To further study the contribution of IFN-Is in the modulation of the intestinal host response during Salmonella infection, we examined the transcription of Ifnβ and Ifnα4 in both the lungs and cecum of mice infected with PR8." (PMID 27149619, 2016).
Splenomegaly (1 paper, 2011). Abnormal increased size of the spleen. "However, protection against splenomegaly was significantly improved when mice had been co-administered vectors encoding IFNα2, IFNα4, IFNα6 or IFNα9 (P < 0.05)." (PMID 21943056, 2011). "Only the co-administration of adenoviral vectors encoding IFNα2, IFNα4, IFNα6 and IFNα9 resulted in strongly improved immune protection of vaccinated mice from subsequent FV challenge infection with high control over FV-induced splenomegaly and reduced viral loads." (PMID 21943056, 2011).
ulcer (1 paper, 2021). "Transcriptional analysis of biopsy tissue indicated that type II interferon, IFNG, not type I (IFNA4 and IFNB1) nor type III (IFNL1, IFNL2, IFNL3) interferons, was the prevalent interferon gene detected in ulcer lesions and 8 weeks post-healed skin." (PMID 34552595, 2021).
infection (40 papers, 2009 to 2025). The state of being infected such as from the introduction of a foreign agent such as serum, vaccine, antigenic substance or organism. "Expression of IRF7 in HEK293 cells led to the induction of the IFNα4 promoter linked to a luciferase reporter gene, which was further increased by infection with Sendai virus (SV), a ssRNA virus known to induce the RIG-I-IRF7 signaling pathway." (PMID 22046272, 2011). "Zc3hav1 deficiency enhanced vesicular stomatitis virus (VSV, a ssRNA virus recognized by RIG-I) infection- or the dsRNA analog poly(I:C) transfection-induced Ifna4 mRNA expression and IRF3 phosphorylation." (PMID 39478149, 2024). "The most highly induced gene was ISG15 at 2 and 4 days post-infection, while IFNa4 was highly induced at day 6 post-infection." (PMID 37651466, 2023). "Consistently, overexpression of miR-543 significantly increased the Ifnb1, Ifna4, and Cxcl10 mRNA levels after infection with SeV, VSV or stimulation with 5’PPP-RNA compared with the NC group in macrophages." (PMID 36028484, 2022). "The expression of Ifnb1, Il6, and Ifna4 were increased in BMDMs from Mettl14+/− mice after infection with SeV or treatment with 5′‐pppRNA, compared to that in wild‐type BMDMs from Mettl14+/+ littermates." (PMID 34047074, 2021). "Consistently, the relative expression of Ifna2, Ifna4 and Ifnb1 was highly decreased in the spleen and LN 16 h post-infection in CD169-Cre+/ki x Usp18fl/fl mice." (PMID 32210083, 2020). "The following experiments were performed with 2 IFNα subtypes (IFNα4 and α5) and further parameters of infection in the liver were analyzed." (PMID 28336921, 2017). "In contrast, the abundance of Ifnb, Ifna4 or Cxcl10 mRNAs induced by RNA mimic poly(I:C) transfection or RNA virus Sendai virus (SeV) infection was comparable between Rnf185 knockdown and wild-type L929 cells." (PMID 28273161, 2017). "Although IFNα4 was only increased 2-fold in exercised mice, the peak IFNα4 response likely occurred prior to 24 hours of infection." (PMID 26110868, 2015). "We found that infection with MVA-N1L virus induces lower levels of IFNA4 and IFNB mRNAs, as well as lower levels of p-TBK1 and p-IRF3." (PMID 24743339, 2014). "We observed that MVA infection of cDCs increased IFNA4 and IFNB mRNA levels by 6-fold and 105-fold, respectively, when compared with untreated cells." (PMID 24743339, 2014). "By contrast, infection with WT VAC increased IFNA4 and IFNB mRNA levels by 2-fold and 6-fold, respectively." (PMID 24743339, 2014). "We found that infection with MVAΔE3L induced higher levels of IFNA4 and IFNB mRNAs than MVA (p<0.001)." (PMID 24743339, 2014). "These ISGs included Ifna2, Ifna4, and Ifnb1, which were induced to high levels in all four strains at 12 hours (>1000-fold) and 24 hours (>100-fold) post-infection, and likely represent early IRF3-mediated gene expression." (PMID 21379341, 2011). "Infection-induced gene expression levels of inflammatory cytokines such as Il6 and Tnf, type I (Ifna4 and Ifnb), and type III IFNs (Ifnl2/3) as well as ISGs such as Mx1, Isg15, and Stat1 peaked simultaneously with peak viral loads on day 2 p.i. in lungs and upper airways." (PMID 36129445, 2022). "timepoint for subsequent experiments because this was when levels of both Ifnb1 and Ifna4 mRNA were at their highest following infection without causing overt suffering to the animal, allowing us to investigate the initial innate immune response." (PMID 31076606, 2019). "Ifnb1 and Ifna4 are unusual amongst type I IFN genes as their expression is induced early in response to infection in an IFN protein-independent manner, although this may be cell type dependent." (PMID 31076606, 2019). "The RNA levels of many type I IFN genes, including Ifna13, Ifna7, Ifna1/5/6, Ifna1/2/5, Ifna4, Ifnab, Ifna12, and Ifnb1, were significantly increased in IEC4.1 cells 24 h post-infection." (PMID 36928642, 2023).
infection (continued). "We observed a significant reduction in the I-IFN Ifnα4 and Ifnb1 mRNAs in HSV-1-infected primary microglia with linc-AhRA overexpression at different times post-infection." (PMID 34646390, 2021). "DKO cells were confirmed to show minimal induction of IFNs (Ifnα4) and IFN-induced gene Rsad2 following 12 hours of infection by either T3DPL or T3DTD." (PMID 32956403, 2020). "We observed approximately 0.5 to 1-log fold greater expression of ISG15, EIF2AK2, OAS1, IFNA4, and IFNB1 in the lungs of rWSN-GH-NS1-Y84F infected mice on days 1 and 3 post-infection compared with the lungs of rWSN-GH-NS1-wt infected mice." (PMID 28498306, 2017). "As expected, the absence of M35 resulted in a higher increase of Ifnb1 and Ifna4 transcription early after infection." (PMID 37289084, 2023). "For example, heat-iMVA infection triggered higher levels of IFN-inducible genes than MVA, including Ifih1 (MDA5), Ddx58 (RIG-1), Oasl2, Oas3, TLR3, Nod1, Ifna4, Ifnb1, Ccl5, Cxcl9, Cxcl10, and members of the guanylate binding protein (Gbp) family, as largely dependent on STING (marked as b)." (PMID 36261460, 2022). "Consistent with the observation from the siRNA knockdown or sgRNA knockout of PRMT9, infection of Prmt9CKO peritoneal macrophages with SeV or stimulation with 5’PPP RNA led to a significant increase in the expression of Ifnb1, Ifnα4, and Cxcl10 mRNA compared with that in Prmt9WT macrophages." (PMID 36028484, 2022). "No significant induction of Ifna4 was observed at 4- or 8h following infection." (PMID 34473814, 2021). "Additionally, we observed increases in the expression of EIF2AK2 (24-fold), OAS1 (10-fold), IFNA4 (10-fold) and IFNB1 (10-fold) in the lungs of rWSN-GH-NS1-Y84F infected mice treated with IFN-β on day 1 post-infection compared with the lungs of infected, but untreated mice." (PMID 28498306, 2017). "We therefore examined gene expression for several important interferon-related genes (IFNα2, IFNα4, IFNβ, IFNαβR, IFNγ, IFNγR, Irf3, Irf7, Mx1, Oas1, IFITM1, IFITM2), along with inflammasome-related genes IL-1β and NLRP3, and chemokines CCL5, CCL7, and CCL12 at d1 post-infection." (PMID 26110868, 2015). "In control DCs, IRF7 bound to both the Ifna4 and Ifnb genes after NDV infection, but not after mock infection." (PMID 19557165, 2009).
tumor (10 papers, 2012 to 2025). "When compared to B16.GFP.gB.luc control tumors, we observed a reduction in type 2 inflammatory cells in B16.IFNα4.gB.luc tumors, most notably ILC2s, tumor-associated macrophages (TAMs) and fibroblasts." (PMID 40367186, 2025). "In a recent study, a comparable CRISPRa technique was utilized to simultaneously activate multiple endogenous genes such as Cd70, Cd80, Cd86, Ifnα4, Ifnβ1, and Ifnγ, triggering anti-tumor adaptive immune clearance of tumor cells in a mouse model." (PMID 41283440, 2025). "Simultaneously, mice were engrafted with either 1 or 10% of cells expressing IL-4 and 99 and 90% of B16.IFNα4.gB.luc cells, respectively, had a significant increase in tumor free survival compared to controls." (PMID 40367186, 2025). "IFNα4 is involved in lymphocyte activation as well as anti-tumor immunity, whereas IFNβ balances expression of pro- and anti-inflammatory agents in addition to inhibiting T cell activation and proliferation." (PMID 39399905, 2024). "Since one possible application of synthetic IFNARs are reinfused cytotoxic T-cells for viral but especially tumor defense, we were interested in the similarities of IFNα4 and our synthetic IFN system." (PMID 36118237, 2022). "We found that the infiltration of CD45+ leukocytes in the tumor tissue was significantly increased on day 14 (8.9% vs. 23%) post IFNα4 treatment." (PMID 34771735, 2021). "Here, we show that engineering tumor-specific T cells to secrete IFNα9 prolonged survival over IFNα4, however this approach relies on constitutive IFNα secretion by the transferred T cells, most likely resulting in elevated levels of IFNα systemically." (PMID 32308653, 2020). "Previously, we showed that, even in the absence of this xenoprotein, we could still observe complete tumor control in 33% of mice engrafted with IFNα9 expressing tumors and delayed tumor progression in those expressing IFNα4." (PMID 40367186, 2025). "Delivery of the canonical type 2 inflammatory cytokine, interleukin-4 (IL-4) into the TME could successfully restore tumor control in the presence of IFNα4 in a preclinical ACT model." (PMID 40367186, 2025). "We observed that heat-iMVA in PRC2-loss murine tumor cells (AT3 [sgEed], SKP605 [sgEed]) not only triggered type I IFN production (e.g., Ifnb1 and Ifna4), but also rescued the PRC2-loss–mediated IFN-γ signaling deficiency, resulting in increased chemokines and Cd274 (Pdl1) expression." (PMID 35852856, 2022). "IFNα4, IFNα5, and IFNα6 had the remarkable capacity to delay tumor growth for well-over 100 days." (PMID 32308653, 2020). "Notably, whereas most subtypes such as IFNα4 could temporarily restrict tumor outgrowth, the IFNα9 subtype promotes immune-mediated tumor rejection, effectively curing a subset of mice from disease." (PMID 40367186, 2025). "However, we found that only IFNα4 reduced the tumor burden in the Myc-CaP CRPC tumor model." (PMID 34771735, 2021). "We administered CD8+ T cell-, CD4+ T cell-, or NK cell-depleting Ab during the IFNα4 treatment of castrated Myc-CaP bearing FVB mice and measured tumor growth." (PMID 34771735, 2021).
immune disorders (1 paper, 2023). "Notably, CCL18 and IFNA4 emerged as prospective peripheral blood markers capable of identifying PTE‐induced immune disorders." (PMID 37700485, 2023).
IFNA4 also shares sentences with these, for which no sentence is quoted: cancer (1 paper); co-infection (1); Crohn disease (1); diabetes (1); H1N1 virus infection (1); hyperglycaemia (1); lupus (1); lupus nephritis (1); neuropathy (1); prostate adenocarcinoma (1); pulmonary hypertension (1); ZIKV infection (1).